IDH1 (isocitrate dehydrogenase (NADP(+)) 1)
Diseases named in the same sentence as IDH1 in open-access papers (continued):
Sharing a sentence is not in itself a finding about the gene and the disease.
tumor (continued). "Staining intensity and tumor cell location were used to determine the status of IDH1 mutations." (PMID 39906459, 2025). "Reduced PD-L1 positivity was linked to higher IDH1 (R132H) expression, indicating that IDH1 (R132H) mutations may alter immune checkpoint pathways and affect tumor immune evasion strategies." (PMID 39906459, 2025). "Additionally, BPTES has been tested in human GBM cell lines with the IDH1 mutation and was found to exhibit profoundly decreased proliferation of the tumor." (PMID 41450919, 2025). "IDH1 mutations: Epigenetic dysregulation drives chemoresistance and tumor progression." (PMID 40863132, 2025). "Our study demonstrates that patients with higher tumor histological grades who had received adjuvant radiotherapy exhibited isocitrate dehydrogenase 1 (IDH1) mutations or presented with wildtype telomerase reverse transcriptase promoter (TERTp) experienced improved OS." (PMID 38893240, 2024). "Interestingly, all patients with IDH1 wild type tumor but with detectable IDH1 mutation in cfDNA had a subtotal resection, and a residual tumor burden was still present in the brain." (PMID 38172718, 2024). "Despite a subgroup analysis was not performed due to the limited sample size, the longer PFS may confirm the presence of the IDH1 mutation, or the presence of a higher level of tumor molecular heterogeneity." (PMID 38172718, 2024). "The number of sequences necessary for statistically significant (p < 0.05, t-test) differentiation between wild-type and variant tumor markers was investigated for IDH1, IDH2, pTERT C228, and pTERT C250, as patient material with confirmed mutations was available." (PMID 39606159, 2024). "This study investigated the association between OS and various factors, including gender, age, distinct tumor grades, the extent of resection, multiple surgeries, radio- and chemotherapy received, mutational profiles in IDH1 and TERTp, EGFR amplification, and MGMTp-met." (PMID 38893240, 2024). "Also, it is suggested that the expression level of tumor-associated genes, such as IDH-1, ATRX, and NLGN3, was correlated with several cognitive domains." (PMID 38315329, 2024). "Tumor-associated IDH1/2 mutations are concentrated in arginine residues at their active sites." (PMID 39273177, 2024). "We conducted univariate cox regression analysis using clinical variables such as age, gender, tumor grade, type of surgery and IDH1 mutation status finding a statistically significant association between IDH1 mutation both in tissue and cfDNA, age, tumor grade and OS." (PMID 38172718, 2024). "Additionally, a greater volume of T2-weighted abnormalities and a higher T2W-to-T1W + contrast ratio of tumor components have also been linked to IDH1 mutations." (PMID 39768232, 2024). "These contrasting conclusions lead us to speculate that IDH1-mutant tumor cells have developed a tolerance to IDH1 mutation and D-2HG, enabling their continued survival." (PMID 38982076, 2024). "IDH1 mutation was also associated with frontal lobe tumour location." (PMID 39767640, 2024). "All IDH1 mutations detected in tumor DNA were also identified in liquid biopsies." (PMID 38191492, 2024). "The independent predictors of better prognosis were tumor grade and IDH1/2 mutations." (PMID 39684714, 2024). "In our study, the frequency of IDH1 mutations differed significantly between tumor types." (PMID 38248076, 2024). "KRAS or NRAS were mutated in six tumours (16%), and IDH1 or IDH2 were mutated in 5 tumours (14%)." (PMID 38877653, 2024). "One possible advantage is the immunosuppressive effect of 2-HG,13,49–51 which could explain how the IDH1 mutation provides a benefit to tumor growth in vivo despite decreased proliferation rates." (PMID 39605316, 2024). "To date, few data have reported the association between IDH1 mutations with tumor localization." (PMID 38172718, 2024). "However, in DDCS, the p.Arg132His mutation-specific IDH1 antibody can help identify less than 20% of these tumours." (PMID 37568740, 2023).
tumor (continued). "Therefore, it is desirable for models of LGG to recapitulate not only the IDH1/2 mutations but also the production of the oncometabolite (R)-2HG in order to accurately reflect LGG tumor biology." (PMID 37051530, 2023). "B4GALT5 and IDH1 are associated with tumour growth and RASSF3 is a tumour suppressor gene." (PMID 36765842, 2023). "Through the rapid intraoperative detection of IDH1-R132H locus mutation, combined with the tumor imaging characteristics, the operator can more accurately infer the molecular subtype and pathological classification of adult diffuse glioma, and then choose the best surgical strategy." (PMID 37029174, 2023). "Studies indicate that the IDH1 mutation may be the initial mutation that initiates tumorigenesis and thus resides in every tumor cell." (PMID 37528157, 2023). "IDH1:p.R132H mutation and 1p/19q co‐deletion were confirmed as driver events in the tumor tissue." (PMID 37533228, 2023). "Tumor molecular markers as IDH1 mutation and MGMT methylation status may provide future treatment targets." (PMID 37071297, 2023). "Tumor-associated macropahges/microglia (TAMs) make up to 50% of the tumor mass and are largely derived from native brain microglia as opposed to peripherally derived macrophages; however, this is dependent on the mutation status (IDH1 versus wild-type)." (PMID 37513708, 2023). "For example, some tumour cells, such as IDH1-mutated CSCs, are mainly metabolized by OXPHOS." (PMID 37108242, 2023). "To identify whether different clinical characteristics of LGG patients are associated with risk scores, we compared tumor histologic grade, gender, age, and IDH1 mutation status between high and low-risk groups in terms of risk scores." (PMID 38022536, 2023). "Mice bearing CT26 tumor with IDH1 mutation showed a worse survival compared to the control mice." (PMID 37741882, 2023). "This could explain why the IC50 values for suppression of different IDH1 mutations in cells were typically much higher than those observed in biochemical assays and suggests that tumor accumulation and/or BBB-penetration may be low as well." (PMID 37049661, 2023). "The defining molecular alterations of this tumour are missense mutations of IDH1 or IDH2, in addition to the deletion of the whole arm of chromosomes 1p and 19q, with mutations in IDH1/2 thought to be an early alteration that drives tumourigenesis prior to the establishment of 1p19q co-deletion." (PMID 37239289, 2023). "CS tumours in adults also comprise a 14q32 lesion but the transformative driver remains unknown, though some CS tumours harbour mutations in IDH1 or IDH2, which supports CS diagnosis." (PMID 36936386, 2023). "In addition to known driver mutations in DNMT3A and IDH1, one patient also had missense tumor specific mutations in the FANCA and FANCM genes." (PMID 36382570, 2023). "Since most of these tumors were IDH-1 mutated, 8 of 15 biopsies could be diagnosed as IZ due to visualization of additional tumor cells." (PMID 36882505, 2023). "Moreover, we have already shown that prognostic relevant molecular markers like IDH1 mutation and tumor stem cells can be addressed by both techniques, with large potential for intraoperative tumor characterization." (PMID 36509907, 2023). "This phenomenon indicates that tumour-derived IDH1 mutations sensitise cells to ferroptosis." (PMID 37645416, 2023). "Additionally, these tumours are defined by mutations in either IDH1 or IDH2, which is an early alteration in tumourigenesis." (PMID 37239289, 2023). "Due to tumor heterogeneity and IDH1 allele heterozygosity, the ability to detect the mutant sequence in a background of wild-type DNA is required for this assay to be useful in the detection of IDH1 SNVs in tumor samples." (PMID 37733671, 2023). "Furthermore, the only GBM patient in this study with a tumor harboring the IDH1 R132H mutation (mtIDH1) appeared to display a highly enhanced response to the belinostat-containing treatment regimen." (PMID 37218937, 2023).
tumor (continued). "IDH1 mutation in cholangiocarcinoma inhibits tumor progression by sensitizing cells to ferroptosis." (PMID 37580393, 2023). "Thus, the initial step for exploring the prognostic role of the MGMT promoter methylation status in the present study was the detection of IDH1/2 mutations in tumor samples by Sanger sequencing." (PMID 36361838, 2022). "Abnormal histone and DNA methylation are emerging as a common feature of tumours with IDH1 and IDH2 mutations and may cause altered stem cell differentiation and eventual tumorigenesis." (PMID 35975235, 2022). "IDH1/2 mutations have been reported in 10–36% of iCCA tumours and FGFR2 fusions in 11–45%." (PMID 35484217, 2022). "IDH1-R132H is the most common type of IDH1 mutation, accounting for 90% of all IDH1 mutations, which is related to the concentration of metabolites produced by this site mutation that is just conducive to tumor cell formation." (PMID 35747806, 2022). "Four tumors with an IDH1 mutation were excluded from the study (tumor samples with a star)." (PMID 36333286, 2022). "Tumor-associated IDH1/2 mutations result in a loss of normal enzymatic function and the abnormal production of 2-hydroxyglutarate (2-HG), which acts as an oncometabolite causing widespread changes in histone and DNA methylation and altering cellular metabolism." (PMID 35267433, 2022). "More caregivers of patients with concurrent mMGMT and IDH1 mutation–positive tumor status reported performing tasks related to “medication organization/administration” compared with patients with concurrent uMGMT and IDH1 mutant tumor status (77% vs 20%, p = 0.047)." (PMID 34510238, 2022). "Most IDH1 mutant tumours always retain one wild-type IDH1 allele, and disruption of the residual wild-type IDH1 allele decreases D-2HG production, which shows that IDH1 mutant-induced D-2HG production is probably dependent on wild-type IDH1 allele." (PMID 35382567, 2022). "For example, IDH2 is capable of compensating mutated IDH1 in tumor cells under hypoxic conditions." (PMID 35985423, 2022). "Additionally, IDH1 mutation, as the main trait of LGGs, was characterized as low tumor mutational load, PD-1+ T cells, or PD-L1 expression." (PMID 35535221, 2022). "Moreover, the targeted DNA NGS analysis revealed an IDH1 (p.R132H) mutation, a surprising finding in this type of tumor." (PMID 36531047, 2022). "Complex I variants were frequently present at high VAFs (mean VAF = 58.8%) with IDH2 mutation in line with co-occurrence in the same tumour clone; however, when present in IDH1-mutant samples they were at lower VAF (mean VAF = 27.3%; Wilcoxon signed-rank test P value = 0.0088)." (PMID 35551192, 2022). "It was hypothesized that IDH1 mutations could mediate tumor development via regulating the immune microenvironment." (PMID 35488886, 2022). "Tumor-derived IDH1 mutations promote lipid ROS accumulation and subsequent ferroptosis." (PMID 36290297, 2022). "Admittedly, mutations of IDH1/2 are considered early events in tumorigenesis and may reveal tumor vulnerabilities that can be exploited for potential therapeutics." (PMID 35912242, 2022). "We therefore postulate that the patient’s acute presentation may have provided the hypoxic stimulus to slow tumour growth via the compromised metabolic capacity of the mutant IDH1 allele, possibly mitigating the effects of the concurrent mutant IDH2 allele." (PMID 36286062, 2022). "Hence, we decided to assess the immune properties of risk score we established in IDH1-associated GBM by using the immunophenoscores of GBM patients from the Tumor Immune Dysfunction and Exclusion (TIDE) database." (PMID 36389748, 2022). "Additionally, PARPi were shown to be more effective on tumor cells with specific mutations, such as IDH1/2." (PMID 35563769, 2022). "Based on these premises, some recent studies have suggested that mutations in IDH1 may modify the tumor immune landscape, and some approaches oriented to use these mutations as therapeutic targets are being tested." (PMID 36142781, 2022).
tumor (continued). "IDH1 has been linked to tumor hypoxic reprogramming, according to a study." (PMID 35924146, 2022). "To date, GoF IDH1 variants in individuals with OD or MS have only been described in tumor tissue." (PMID 36480544, 2022). "Moreover, age, tumor grade, IDH-1 mutations, and inflammation-nutrition score were independent prognostic factors in the multivariate analysis and thus were included in the nomogram model." (PMID 35495765, 2022). "Overall, 23 patients (14%) had an IDH1 mutation–positive tumor." (PMID 34510238, 2022). "In a study of human GBM mutations in IDH1 wild-type, the tumor-free SVZ had TERT promoter mutations, suggesting this could be an early mutation in the progression from NSC to GBM." (PMID 35359410, 2022). "Therefore, although initially suspected to have tumour suppressive function, IDH1 and IDH2 are both oncogenes, encoding oncogenic enzymes: the mutant enzymes catalyse neomorphic reactions with the resultant d-2-HG product." (PMID 36286062, 2022). "However, according to the multivariate Cox regression analysis, only the tumor grade and IDH1 mutation were the best predictors of patient OS in our study cohort." (PMID 36232448, 2022). "However, it is very unlikely that this patient harbored a homozygous IDH1-mutant cell clone, given the very different VAFs for each mutation in the primary tumor, and that only one mutation (R132C) was detected in plasma." (PMID 35740557, 2022). "Together with our previous studies showing that IDH1 hotspot mutations are intrinsically tumor suppressive, these findings may provide an explanation for the rare occurrence of IDH1 and IDH2 hotspot mutations in human cancer." (PMID 34440884, 2021). "FGFR1 mutations have also been implicated in tumor pathogenesis, as well as IDH1." (PMID 34069450, 2021). "Besides enhancement quality, other VASARI features of strong predictive power for IDH1 mutation status included deep white matter invasion, tumor location, proportion of necrosis, and T1/FLAIR ratio." (PMID 33553421, 2021). "Our findings together with TCGA data analysis indicated that AGII and AGIII harboring IDH1 mutation may decrease tumor cell fitness by lowering Glu, GSH, and resistance to oxidative stress." (PMID 33910646, 2021). "Therefore, we infer that genetic status, by means of IDH1 mutation status, is more reflective than the histologic class, regarding oxygen metabolism or tumor vascularization." (PMID 34671241, 2021). "Additional studies investigating the functional impact of IDH1 mutations proposed that IDH1 may function as a tumor suppressor that, when inactivated by a mutation, likely contributes to tumorigenesis." (PMID 33673213, 2021). "In the IDH1 wild-type of G4 and G3-rich cluster, genes involved in the mitotic cell cycle and degradation of the extracellular matrix that are associated with malignancy of tumour in the Reactome 2020 database were more highly expressed than in LGG." (PMID 34205437, 2021). "Therefore, IDH1 and its associated metabolites are beneficial for the maintainence of tumor survival and the harsh external environment." (PMID 34234856, 2021). "The development of IDH1/2 variant inhibitors has been driven by the hypothesis that reducing levels of the ‘oncometabolite’ 2HG may reduce tumour progression, halt malignant transformation, and/or improve patient survival." (PMID 34854890, 2021). "Furthermore, high expression levels of IDH1 and C3 were obviously linked to enhanced tumor infiltration by macrophages, DCs, and/or B cells." (PMID 34603319, 2021). "Cancer-linked IDH1/2 variants have reduced wild-type (wt) activity, but gain the ability to convert 2OG to the ‘oncometabolite’ 2-hydroxyglutarate (2HG), resulting in substantially elevated 2HG levels in tumours bearing IDH mutations." (PMID 34725432, 2021).
tumor (continued). "Given that SVZ contact and IDH1 mutation are potent factors predicting patient survival time and tumor relapse, it is unknown whether the prognostic performance would be improved with combined use of SVZ contact and IDH1 mutation." (PMID 34490090, 2021). "However, patients with an IDH-1wildtype GBM had a significantly higher edema to tumor ratio compared to their IDH-1 mutated peer group." (PMID 33868245, 2021). "Tumor-derived IDH1 mutations impair formation of the enzyme product, α-ketoglutaric acid (α-KG)." (PMID 34707087, 2021). "Our data show that, even within the prognostic DNA methylation subtypes, patients harbouring non-R132H IDH1/2-mutated tumours had a significantly longer survival compared to those harbouring IDH1R132H-mutated tumours, regardless of the classifier used (Online resource)." (PMID 33740099, 2021). "Furthermore, 2-HG is also taken up by cells in the microenvironment of IDH1/2-mutated tumor cells, e.g., immune and stromal cells." (PMID 33916994, 2021). "In addition to transcriptome profiles, the TCGA includes phenotypic and genetic information, which allowed us to include tumor grade and IDH1/2 mutational status as previously associated covariates in our model." (PMID 34101353, 2021). "In contrast, the ALPS index is measured in the periventricular region outside of the tumor and, thus, may serve as an alternative marker for IDH1 mutation prediction." (PMID 34631582, 2021). "Although our analyses of tumor responses and overall survival are based on very small numbers and late-stage cancer patients, alternative combination regimens disrupting the metabolism in IDH1/2-mutated cancers should be investigated in future studies." (PMID 34069550, 2021). "However, GBM patients displaying IDH-1 wildtype had significantly higher edema to tumor ratio than patients displaying an IDH-1 mutation (p=0.01)." (PMID 33868245, 2021). "21/104 (20%) tumours were wild‐type (WT) for hot spot IDH1/2 mutations." (PMID 34528398, 2021). "Again, the vast majority of probes had lower DNA methylation levels in IDH1R132H mutated tumours (n = 83) compared to non-R132H IDH1/2- mutated tumours (n = 11) and the most differentially methylated probes were those partially methylated in IDH1R132H mutated tumours." (PMID 33740099, 2021). "Moreover, our biochemical data together with the previous biochemical data can explain why the cancer-associated IDH1 or IDH2 mutations cause drastic accumulation of D-2-HG in the tumor cells." (PMID 33431826, 2021). "Furthermore, the IDH1-mutated tumors were recently targeted by a vaccine that exhibited vaccine-mediated tumor response in the majority of cases." (PMID 35996504, 2021). "Sanger sequencing using DNA derived from tumor tissues revealed an IDH1 R132C mutation." (PMID 34685506, 2021). "Similarly, IDH1 IRS class is significantly associated (p = 0.013) with small tumour size with 47.7% of larger tumours displaying strong IRS and only 20% of smaller tumours had a strong IRS class." (PMID 33367952, 2021). "By utilization of digital droplet PCR, we were able to detect tumor-specific IDH1 hotspot mutations in ctDNA, which may facilitate the monitoring of tumor response during therapy." (PMID 34069550, 2021). "The patterns of age and IDH1 mutations were analysed according to histological tumour grade." (PMID 34205437, 2021). "We identified four PODNL1 CpG sites, cg07425555, cg26969888, cg18547299, and cg24354933, which were associated with unfavorable overall survival (OS) and disease-free survival (DFS) in univariate and multivariate analysis after adjusting for age, gender, tumor-grade, and IDH1-mutation." (PMID 34830454, 2021). "Thus, IDH1 has been suggested to act as a tumor suppressor, which, when inactivated by mutation, contributes to tumorigenesis in part by induction of the HIF-1α pathway." (PMID 34073734, 2021). "IDH1 mutation was present in 83% (85/102) of the tumours in the LGG cohort." (PMID 34771529, 2021).